SOCS2-AS1 (SOCS2 antisense RNA 1)
Gene: Long non-coding RNA gene on chromosome 12 (93,501,115 to 93,571,768, reverse strand). Ensembl gene ENSG00000246985.
Diseases named in the same sentence as SOCS2-AS1 in open-access papers:
SOCS2-AS1 is named in the same sentence as 4 diseases in open-access papers, as found by Europe PMC text mining. Sharing a sentence is not in itself a finding about the gene and the disease. The quoted sentences say what the papers report.
colorectal cancer (1 paper, 2023). A primary or metastatic malignant neoplasm that affects the colon or rectum. "SOCS2AS1 promotes tumour progression in prostate cancer but inhibits tumour progression in epithelial, ovarian, and colorectal cancer." (PMID 36844873, 2023).
SOCS2-AS1 also shares sentences with these, for which no sentence is quoted: liver cancer (1 paper); prostate carcinoma (1); tumour (1).